TRH (thyrotropin releasing hormone)
Description:
As a component of the hypothalamic-pituitary-thyroid axis, it controls the secretion of thyroid-stimulating hormone (TSH) and is involved in thyroid hormone synthesis regulation. It also operates as modulator of hair growth. It promotes hair-shaft elongation, prolongs the hair cycle growth phase (anagen) and antagonizes its termination (catagen) by TGFB2. It stimulates proliferation and inhibits apoptosis of hair matrix keratinocytes.
Synonyms: Pro-TRH; TRF
Tractability: Antibody: its Gene Ontology location is reachable by antibodies, with high confidence; UniProt places it where antibodies can reach, with medium confidence; UniProt predicts a signal peptide or a membrane-spanning region.
Gene: Protein-coding gene on chromosome 3 (129,974,688 to 129,977,935, forward strand). Ensembl gene ENSG00000170893.
Subcellular location: Secreted
Pathways (Reactome):
Signal Transduction: G alpha (q) signalling events; Peptide ligand-binding receptors
Gene Ontology:
Molecular function: protein binding; thyrotropin-releasing hormone activity
Biological process: adenylate cyclase-activating G protein-coupled receptor signaling pathway; cell-cell signaling; signal transduction; hormone-mediated signaling pathway
Cellular component: extracellular region; secretory granule
Genetic constraint (gnomAD): Loss-of-function variants: 7 observed, 6.2 expected, observed/expected ratio (o/e) 1.13, 90% interval 0.63 to 1.84. That is too few expected variants to judge how well the gene tolerates losing a copy. Missense variants: 318 observed, 316.25 expected, observed/expected ratio (o/e) 1.01, 90% interval 0.92 to 1.1. Synonymous variants: 131 observed, 129.11 expected, observed/expected ratio (o/e) 1.01, 90% interval 0.88 to 1.17.
Homologues: Orthologues: chimpanzee TRH (98% identical), macaque TRH (92% identical), dog TRH (79% identical), rabbit TRH (79% identical), pig TRH (76% identical), rat Trh (58% identical), mouse Trh (57% identical), tropical clawed frog trh (30% identical), zebrafish trh (29% identical).
Diseases named in the same sentence as TRH in open-access papers:
TRH is named in the same sentence as 189 diseases in open-access papers, as found by Europe PMC text mining. Sharing a sentence is not in itself a finding about the gene and the disease. The quoted sentences say what the papers report.
hypothyroidism (79 papers, 2007 to 2025). Abnormally low levels of thyroid hormone. "In hypothyroidism, prolonged feedback mechanisms can cause an increase in thyrotropin-releasing hormone (TRH) from the hypothalamus, which stimulates the production of PRL." (PMID 40150506, 2025). "Elevation in TRH can also result in hyperprolactinemia; hyperprolactinemia can cause amenorrhea and hirsutism, which can be remediated with treatment of hypothyroidism." (PMID 40861719, 2025). "In contrast, subclinical or overt hypothyroidism is associated with exaggerated prolactin response to TRH which is reversed after achieving euthyroidism." (PMID 39037546, 2024). "The production of the few amidated peptides tested was not greatly altered by PAM heterozygosity, but the production of amidated TRH in the hypothalamus was compromised and the mice were deficient in their pituitary response to hypothyroidism." (PMID 37388215, 2023). "Hypothyroidism causes an increase in the levels of thyroid releasing hormone (TRH) which in turn stimulates secretion of thyroid stimulating hormone (TSH) and prolactin (PRL) and PRL inhibits the synthesis and secretion of gonadotrophins." (PMID 28723963, 2017). "Hypothyroidism by virtue of raised thyrotropin releasing hormone (TRH) causes altered follicle stimulating hormone (FSH)/luteinizing hormone (LH) ratio and raised dehydroepiandrosterone (DHEA-S) levels." (PMID 27478827, 2016). "Primary hypothyroidism is the principal cause of hypothyroidism, but other causes include central deficiency of thyrotropin-releasing hormone (TRH) or thyroid-stimulating hormone (TSH)." (PMID 26644879, 2015). "The authors have concluded that the TSH response to TRH is a useful tool for the evaluation of infants with mildly abnormal TSH levels and that infants with TSH levels >35 IU/mL after TRH are at risk of hypothyroidism." (PMID 26831555, 2015). "Although thyroidectomy caused severe hypothyroidism in TRH-deficient mice, the increases in serum TSH levels and pituitary TSHβ mRNA levels were insufficient." (PMID 22792320, 2012). "Thyroid hormone levels are usually normal, even if the patients often show symptoms of hypothyroidism and there is some evidence suggesting an association with abnormal thyrotropin-releasing hormone (TRH) stimulation tests." (PMID 23213512, 2012). "In hypothyroidism, there is a loss of feedback inhibition on TRH production from the hypothalamus." (PMID 39754184, 2025). "Finally, thyroid-stimulating hormone (TSH) levels should be evaluated, as hypothyroidism causes an elevation in thyrotropin-releasing hormone (TRH) and subsequently TSH." (PMID 40861719, 2025). "For example, increased levels of TRH may raise prolactin levels, contributing to the amenorrhea associated with hypothyroidism." (PMID 28723963, 2017). "Hypothyroidism may cause pituitary and thyrotrophic hyperplasia which result in elevated TRH and prolactin release." (PMID 26091810, 2015). "According to the medical literature, this variability is explained by the fact that pituitary hyperplasia is more frequently observed in cases of severe and prolonged hypothyroidism, where TRH stimulation is sustained." (PMID 41257121, 2025). "Thyrotropin-Releasing Hormone (TRH) is a judgement index for evaluating the therapeutic effect of hyperthyroidism and hypothyroidism." (PMID 40022834, 2025). "Such decrement can be supported by additional parameters of thyroid hormones action (e.g., cholesterol, heart rate, hypothyroidism questionnaire) or dynamic tests (e.g., TRH test or nocturnal TSH surge)." (PMID 40719952, 2025). "The degree of pituitary hyperplasia depends on the duration and severity of hypothyroidism, as well as on the individual sensitivity of the pituitary to TRH." (PMID 41257121, 2025). "Corticosteroids can also induce hypothyroidism by suppressing TSH secretion via inhibiting TRH gene expression in the hypothalamus." (PMID 38975517, 2024).
hypothyroidism (continued). "Our study suggested that two-thirds of SCH showed exaggerated TSH responses in the TRH stimulation test, revealing hypothyroid state." (PMID 39749109, 2024). "Experimentally induced hypothyroidism prolonged life in rodents and the administration of TRH to old mice showed aging-delaying and aging-reversing effects." (PMID 37191429, 2023). "In a TRH stimulation test, he had a diminished increase of TSH in response to TRH, indicating a central cause of hypothyroidism." (PMID 35456429, 2022). "Among women with hypothyroidism, hyperprolactinemia is induced by thyrotropin-releasing hormone (TRH)." (PMID 35291534, 2022). "Hypothyroidism leads to a compensatory increase in the production of thyrotropin-releasing hormone (TRH) by the hypothalamus, which in turn results in suppression of dopamine production, resulting in excessive prolactin secretion, i.e. hyperprolactinemia." (PMID 36733805, 2022). "Contrary to this effect, it is reported that there is a reduction in TSH response to TRH in depression which leads to hypothyroidism." (PMID 33995058, 2021). "In tertiary hypothyroidism, a decrease in thyroid hormone arises from inadequate secretion of thyrotropin-releasing hormone (TRH) from the hypothalamus." (PMID 34576309, 2021). "Various milestones should be reached to target peripheral TRH-DE activity to improve thyroid status in hypothyroidism." (PMID 32457627, 2020). "If there is no change in the serum TSH values following the administration of TRH, the test is interpreted as secondary hypothyroidism; in hypothalamic (tertiary) hypothyroidism, TSH values increase." (PMID 32150810, 2020). "The difference between secondary and tertiary hypothyroidism is established by performing a thyrotropin-releasing hormone (TRH) stimulation test." (PMID 32150810, 2020). "It is well established that the hypothalamus regulates pituitary TSH secretion by releasing thyrotropin-releasing hormone (TRH) and excess TSH is associated with iodine deficiency and hypothyroidism." (PMID 31010095, 2019). "TSH biopotency in our patient was not only reduced but also insensitive to TRH stimulation, which is consistent with our experimental findings that the ultimate molecular mechanism for hypothyroidism in this disorder is the decrease of TRHR expression." (PMID 28262687, 2017). "Low thyroid hormone levels, increasing thyrotropin-releasing hormone secretion, stimulates lactotrophs to produce prolactin, while hypothyroidism was found to induce sexual dysfunction." (PMID 26902871, 2016). "The effects of TRH administration indicated that this central hypothyroidism was probably of hypothalamic origin." (PMID 25248098, 2014). "This is supported by the report that pituitary-specific GATA2-knockout mice exhibit reduced TSHβ expression in hypothyroidism, where stimulation by TRH should be elevated." (PMID 21533184, 2011). "In hypothyroidism, the majority of TRβ2 in thyrotroph is unliganded and TRH production in the hypothalamus is increased." (PMID 21533184, 2011). "First, TRβ-knockout mice and wild-type mice exhibited comparable TSHβ expression in hypothyroidism where TRH secretion from the hypothalamus is elevated." (PMID 21533184, 2011). "Second, TSH level in hypothyroidism was severely impaired in TRH/TRβ-double knockout mice compared with wild-type or TRβ-knockout mice, suggesting that elevation of TSHβ expression requires the TRH signal even when inhibition by T3/TR is released." (PMID 21533184, 2011). "It appears counterintuitive that the bioactivity of TSH decreases in the hypothyroid state as higher bioactivity of TSH is anticipated in hypothyroidism promoted by an increased hypothalamic TRH drive." (PMID 21048840, 2010). "Hypothyroidism results in increased levels of thyrotropin-releasing hormone, which increases prolactin secretion." (PMID 20046401, 2009).
hypothyroidism (continued). "Chronic hypothyroidism may induce pituitary hyperplasia due to elevated thyrotropin-releasing hormone, impairing corticotrope function and HPA axis integrity." (PMID 41446490, 2025). "The lack of negative feedback in hypothyroidism causes excessive secretion of TRH, and conduce to a proliferation of TSH secreting cells, which results in compensatory enlargement of the pituitary gland (TRH-dependent hyperplasia)." (PMID 38650008, 2024). "As nesfatin‐1 neurons co‐localized with TRH and GnRH neurons in the hypothalamus, it could play a role in centrally hypothyroidism induced testicular dysfunction." (PMID 38268116, 2024). "Disturbances in the hypothalamic regulation may explain these findings, e.g., increased TRH secretion being present in hypothyroidism might be responsible for the low apelin level in this state." (PMID 36187132, 2022). "Hypothyroidism may also result in hyperprolactinemia due to elevated levels of thyrotropin-releasing hormone (TRH), leading to infertility." (PMID 35054403, 2021). "Meanwhile, since the mild tertiary hypothyroidism was observed in the TRH-KO mice, lower levels of thyroid hormone likely alter the intrinsic excitability of PCs, which could affect LTP and/or RP." (PMID 30618637, 2018). "Hypothyroidism must also be evaluated for, as TRH stimulates prolactin secretion." (PMID 27446618, 2016). "Hypothyroidism can arise as primary from the thyroid gland when there is a defect in thyroid hormone synthesis and release centrally from the hypothalamic-pituitary-thyroid axis when there is a defect in either TRH or TSH signaling to the thyroid." (PMID 26644879, 2015). "Secondary hypothyroidism is caused by a deficiency in thyroid stimulating hormone (TSH) released from the anterior pituitary, and tertiary hypothyroidism is caused by a deficiency in thyrotropin-releasing hormone (TRH) released from the hypothalamus, which reduces the amount of TSH released." (PMID 40150555, 2025). "Elevated ISP compresses the pituitary stalk, and together these factors interfere with the delivery of hypothalamic hormones—such as TRH, CRH, and GnRH—resulting in secondary hypothyroidism, adrenal insufficiency, or hypogonadism." (PMID 41480352, 2025). "After removing palindromic SNPs and outliers, we obtained 26, 12, 65,11,258,22,26,16,20, and 23 SNPs for GD, HT, hypothyroidism, hyperthyroidism, TC, TSH, TRH, THRα, TP and TG, respectively." (PMID 39205687, 2024). "As a result of SNP filtering, 18, 18, 18,18,5,17,17,17,17,17 and 4 SNPs were included for GD, HT, hypothyroidism, hyperthyroidism, TC, TSH, TRH, THRα, TP, TG and TBG, respectively, in final analysis." (PMID 39205687, 2024). "In hypothyroidism, the hypothalamus increases TSH production in the pituitary gland by producing thyrotropin-releasing hormone (TRH), which is required for normal physiological elevation of thyroxine levels." (PMID 34305584, 2021). "Lithium inhibits the release of thyroid hormones and increases TRH-stimulated TSH, leading to goiter, clinical and subclinical hypothyroidism, but rarely to hyperthyroidism." (PMID 34674686, 2021). "In fact, in vitro studies show that mitotane reduces both the expression and secretion of TSH in a dose-dependent manner and blocks the TSH response to thyrotropin-releasing hormone (TRH), determining central functional hypothyroidism." (PMID 34638485, 2021). "The present data suggest that TCS-induced hypothyroidism presents the same scenario, as the elevated levels of serum PRL, TSH and TRH in 10-TCS mice were corrected by L-T4 administration." (PMID 29403355, 2018). "Due to the loss of thyroxine feedback inhibition and the subsequent overproduction of thyrotropin-releasing hormone (TRH), long-standing hypothyroidism results in hyperplasia of the thyrotroph cells and subsequent enlargement of the pituitary gland." (PMID 21473748, 2011).
hypothyroidism (continued). "Preclinical hypothyroidism is characterized by normal thyroxine (T4) and free thyroxine (FT4), normal basal TSH and TSH slightly increased after the Thyrotropin-releasing Hormone (TRH) test." (PMID 20492708, 2010). "For this reason we used the information provided by the TRH stimulation test for the evaluation of basal TSH levels in relation to the identification of latent and/or overt hypothyroidism." (PMID 17678551, 2007). "MR analysis showed that there had no causal association between PSC and hypothyroidism, AT, TC, TSH, TRH, TBG, THRα, TP and TG." (PMID 37928559, 2023). "As secondary hypothyroidism is overlooked in this way, when financial resources are available it is recommended to measure FT4 to screen for central (i.e. secondary, due to insufficient secretion of TRH or TSH) hypothyroidism." (PMID 36034431, 2022). "In contrast, elevated TRH can increase levels of TSH and PRL in patients with hypothyroidism." (PMID 26091810, 2015). "Briefly, low levels of serum TH in hypothyroidism result in an increased release of thyroid stimulating hormone (TSH) by the pituitary, under the influence of hypothalamic thyrotropin releasing hormone (TRH)." (PMID 23408906, 2013). "TRH stimulation test was applied to 61 patients without overt hypothyroidism or overt hyperthyroidism." (PMID 21448329, 2011). "Most cohort studies predicted the role of TSH and autoantibody in future hypothyroidism, but few previous reports were available regarding the predictive ability of basal TSH and autoantibodies to predict the present hypothyroid state with an exaggerated TRH stimulation test in SCH." (PMID 39749109, 2024). "However, there was no causal effect between PSC and AT, hypothyroidism, TC, TSH, TRH, TBG, THRα, TP, TG." (PMID 37928559, 2023). "Hypothyroidism increases Thyrotropin Releasing Hormone (TRH) transcription and secretion from the hypothalamus but in healthy pre-menopausal women hypophyseal stimulation by TRH of only TSH, LH and prolactin, but not of FSH, was observed." (PMID 36005590, 2022). "Studies on anencephalic human fetuses and studies in animals that underwent surgical removal of the maternal and fetal hypothalamus or to which TRH antibodies were administered demonstrated that the role of TRH is probably auxiliary rather than major, since no fetal hypothyroidism was noted." (PMID 34071168, 2021). "In a rat model of subclinical hypothyroidism-induced depression, resveratrol not only reduced plasma corticosterone levels and depressive behaviors, but also hypothalamic CRH mRNA expression and levels of thyrotropin-releasing hormone (TRH) and thyroid stimulating hormone (TSH)." (PMID 30200269, 2018). "Considering the crucial role of nesfatin-1 in energy and glucose metabolism, we speculated that it might act as a regulatory factor of thyroid function by adjusting AMPK activity and TRH secretion in T2DM patients, thereby resulting in the subclinical hypothyroidism." (PMID 24995340, 2014). "In addition, the serum TSH level was more profoundly affected in animals with severe hypothyroidism in the absence of TRH." (PMID 22792320, 2012). "Hence, we speculate that diminished TRH and TSH secretion as well as the absence of normal feedback control caused by degeneration and impaired function of the hypothalamus and pituitary gland, result in the development of hypothyroidism in patients with AD during the mid to late stages." (PMID 38419953, 2024).